GPR61 (G protein-coupled receptor 61)
Description:
Orphan G protein-coupled receptor. Constitutively activates the G(s)-alpha/cAMP signaling pathway. Shows a reciprocal regulatory interaction with the melatonin receptor MTNR1B most likely through receptor heteromerization. May be involved in the regulation of food intake and body weight (By similarity).
Synonyms: BALGR; GPCR3
Tractability: Small molecule: a structure with a bound ligand is known; it belongs to a druggable protein family. Antibody: UniProt places it where antibodies can reach, with high confidence; its Gene Ontology location is reachable by antibodies, with high confidence; UniProt predicts a signal peptide or a membrane-spanning region.
Target class: Family A G protein-coupled receptor; Membrane receptor
Gene: Protein-coding gene on chromosome 1 (109,539,872 to 109,548,406, forward strand). Ensembl gene ENSG00000156097.
Subcellular location: Cell membrane; Endosome membrane
Gene Ontology:
Molecular function: arrestin family protein binding; protein binding; G protein-coupled receptor activity
Biological process: ligand-independent adenylate cyclase-activating G protein-coupled receptor signaling pathway; G protein-coupled receptor signaling pathway
Cellular component: endosome; endosome membrane; plasma membrane; receptor complex; membrane
Genetic constraint (gnomAD): Loss-of-function variants: 16 observed, 29.69 expected, observed/expected ratio (o/e) 0.54, 90% interval 0.36 to 0.82. The upper end of that interval is the gene's LOEUF score, 0.82, which puts it in group 3 of 6, group 1 being the genes least tolerant of losing a copy. Missense variants: 399 observed, 604.4 expected, observed/expected ratio (o/e) 0.66, 90% interval 0.61 to 0.72. Synonymous variants: 238 observed, 251.79 expected, observed/expected ratio (o/e) 0.95, 90% interval 0.85 to 1.05.
Homologues: Orthologues: chimpanzee GPR61 (100% identical), macaque GPR61 (99% identical), rabbit GPR61 (98% identical), rat Gpr61 (96% identical), mouse Gpr61 (96% identical), pig GPR61 (96% identical), dog GPR61 (95% identical), tropical clawed frog gpr61 (59% identical), zebrafish gpr61 (56% identical). Paralogues in human: GPR62 (27% identical), GPR135 (20% identical), GPR176 (17% identical).
Diseases named in the same sentence as GPR61 in open-access papers:
GPR61 is named in the same sentence as 11 diseases in open-access papers, as found by Europe PMC text mining. Sharing a sentence is not in itself a finding about the gene and the disease. The quoted sentences say what the papers report.
Obesity (4 papers, 2014 to 2025). Accumulation of substantial excess body fat. "Nevertheless, we conclude that our findings contribute to the general knowledge about GPR61’s role in health and disease, and add relevant information about severe obesity-linked mutations of this receptor in the overexpressed conditions." (PMID 40133016, 2025). "Then we analyzed samples from the UK10K obesity screen for the presence of missense mutations in the GPR61 gene and compared them with the normal population found in the gnomAD database." (PMID 40133016, 2025). "Our study was not aimed to assess or to prove causation between the presence of GPR61 mutations and (severe) obesity." (PMID 40133016, 2025). "The orphan GPCR GPR61 had been linked to the regulation of metabolism and, here, we identify 34 mutations in the GPR61 gene which are present with much higher frequency in severe obesity samples from the UK10K obesity screen compared to the normal population." (PMID 40133016, 2025). "We compared the frequency of mutations in GPR61 with MC4R to assess whether similar patterns of mutation frequency could be observed in the gene with the established role in obesity and metabolic disorders." (PMID 40133016, 2025). "From our comprehensive analysis of 480 severe obesity samples obtained from the UK10K study, we identified 34 different missense mutations in the GPR61 gene." (PMID 40133016, 2025). "The data support the notion that GPR61 can act as a promising target in obesity and its functions should be explored in future studies." (PMID 40133016, 2025). "Knockout studies of GPR61 in mice exhibit hyperphagia-induced obesity and higher plasma insulin levels." (PMID 25502755, 2014). "We use this analogy to suggest that the high frequency of mutations observed in GPR61, and even the higher cumulative number of mutations than for MC4R, may indicate the role of GPR61 in metabolism/obesity." (PMID 40133016, 2025). "Another incentive for this study was to test the notion emerging from a few previously published studies that GPR61 has a role in metabolic regulation and if so, postulate that it can be grouped with other GPCRs with established links to obesity (eg. glucagon-like peptide-1 receptor)." (PMID 40133016, 2025). "The first model included genetic variants known to be associated with obesity—specifically, ADCY3 rs11676272, CLOCK rs1801260, GPR61 rs41279738, FTO rs1421085, RP11-775H9.2 rs1296328, SLC22A3 rs9364554, and TFAP2B rs734597—and explained 8.3% of the variance in BMI." (PMID 39766774, 2024). "Previous GWASs have demonstrated the association of the studied polymorphic loci ADCY3 rs1167627272, CLOCK rs1801260, FTO rs1421085, GPR61 rs41279738, RP11-775H9.2 rs1296328, SLC22A3 rs9364554, and TFAP2B rs734597 with obesity-related phenotypes." (PMID 39766774, 2024).
albinism (1 paper, 2017). A congenital disorder characterized by partial or complete absence of melanin pigment in the eyes, hair, or skin. "Although no differential expression of GPR143 was observed as in mammals’ albinism, the identification of other G-protein coupled receptor including GPR21 and GPR61 may imply their possible involvement in fish albinism." (PMID 28777813, 2017).
Autoimmunity (1 paper, 2017). The occurrence of an immune reaction against the organism's own cells or tissues. "Given the lack of reports about physiological effects mediated by GPR61, a potential role in Th17‐dependent immunity and autoimmunity may warrant further investigation." (PMID 29226084, 2017).
Cachexia (1 paper, 2023). Severe weight loss, wasting of muscle, loss of appetite, and general debility related to a chronic disease. "Through efforts to develop a small molecule therapeutic targeting GPR61 for the treatment of cachexia, we have discovered a sulfonamide inverse agonist tool compound that exhibits potent and selective inhibition of GPR61 constitutive activity." (PMID 37741852, 2023). "GPR61 is an orphan GPCR of interest for treatment of appetite disorders, such as obesity and cachexia." (PMID 37741852, 2023).
GPR61 also shares sentences with these, for which no sentence is quoted: type 2 diabetes (2 papers); asthma (1); autoimmune disease (1); cancer (1); gastric cancer (1); lung carcinoma (1); metabolic disorders (1).